IGFBP3 (insulin like growth factor binding protein 3)
Diseases named in the same sentence as IGFBP3 in open-access papers (continued):
Sharing a sentence is not in itself a finding about the gene and the disease.
dysplasia (1 paper, 2021). A usually neoplastic transformation of the cell, associated with altered architectural tissue patterns. "Data from our previous retrospective study suggested a role for reduced IGFBP3 secretion in both Barrett’s onset and the evolution toward dysplasia/adenocarcinoma." (PMID 34684639, 2021).
endometrial polyp (1 paper, 2018). A benign nodular lesion protruding above the surface of the endometrium. "The purpose of this study was to examine the association of polymorphisms IGF-1 CA(n) and IGFBP3 rs2854746 with risk of endometrial polyps." (PMID 30643822, 2018). "We found a statistically significant association between IGFBP3 rs2854746 polymorphism and endometrial polyp risk, with CG genotype having a protective effect." (PMID 30643822, 2018). "However, some genotypes of the IGFBP3 polymorphism rs2854746 are inversely related to endometrial polyp." (PMID 30643822, 2018). "The IGFBP3 rs2854746 analyses showed the CG genotype having a protective effect for endometrial polyp (OR=0,37; IC 95%= 0,19-0,73), fact also observed when grouping CG and GG carriers (OR=0,51; IC 95%= 0,28-0,93)." (PMID 30643822, 2018). "The aim of the present study was to investigate the relationship between risk of endometrial polyp and genotypes of IGF-1 CA( n) and IGFBP-3 rs2854746 polymorphisms." (PMID 30643822, 2018). "Furthermore, the disequilibrium between IGF-1 and IGFBP3 levels could be the triggering factor for endometrial polyp development." (PMID 30643822, 2018).
erectile dysfunction (1 paper, 2016). Persistent or recurrent inability to achieve or to maintain an erection during sexual activity. "Gene transfer of IGFBP-3 shRNA could improve erectile function via the restoration of cavernous IGF-1 bioavailability and an increase of cavernous cGMP concentration in the pathogenesis of erectile dysfunction in streptozotocin-induced diabetic rats." (PMID 27136480, 2016). "Here we provide two lines of evidence that gene transfer of IGFBP-3 shRNA could improve erectile function via the restoration of cavernous IGF-1 bioavailability and an increase of cavernous cGMP concentration in the pathogenesis of erectile dysfunction in STZ-induced diabetic rats." (PMID 27136480, 2016).
haemorrhage (1 paper, 2022). "The protein levels of IGFBP3, MMP9 and PDGF-BB were significantly higher in the denser haemorrhage group." (PMID 36473885, 2022).
head and neck cancer (1 paper, 2021). A primary or metastatic malignant neoplasm affecting the head and neck. "The prognostic role of IGFBP-3 has been previously reported in head and neck cancer." (PMID 33801272, 2021).
helminth infections (1 paper, 2020). "To address this, we conducted a study in the adult population living in an area endemic for helminth infection to evaluate the association between STH infections and free IGF-1 concentration as well as its main binding protein, IGFBP-3." (PMID 33149205, 2020). "Subsequently, to assess causality, we investigated the effect of anthelmintic treatment on serum free IGF-1 and IGFBP-3 levels to evaluate the effect of helminth infections on IGF system." (PMID 33149205, 2020). "Our study showed that helminth infection in adults is associated with lower free IGF-1 levels but not with IGFBP-3 and albendazole treatment significantly increases free IGF-1 levels in the study population." (PMID 33149205, 2020). "Here, we assessed the impact of helminth infection on free IGF-1 and its major binding protein, IGFBP-3, in adults." (PMID 33149205, 2020). "When helminth infection was detected based on microscopy, a less sensitive method that misses infection in 10.3% of the subjects, the difference in the level of free IGF-1 and IGFBP-3 between STH-infected and non-infected subjects fell short of statistical significance." (PMID 33149205, 2020).
Hepatic failure (1 paper, 2018). "At the six-month follow-up, cirrhotic patients with IGFBP3 levels lower than 6 ng/mL died from hepatic failure and/or bleeding during this period." (PMID 29702590, 2018). "The increased rate of serum IGF1/IGFBP3 is described in patients with HCC, compared to patients with cirrhosis and liver failure." (PMID 29702590, 2018).
HIV-1 infection (1 paper, 2012). The type species of lentivirus and the etiologic agent of acquired immunodeficiency syndrome (AIDS). "HIV-1 infection increases the proteolysis of IGFBP-3, thus decreasing IGFBP-3 levels and in turn reducing the amount of IGF-1 in circulation." (PMID 24052871, 2012).
hyperemia (1 paper, 2022). The presence of an increased amount of blood in a part or organ; engorgement. "The relief of the cuff pressure in the LI + BFR protocol and the decrease in muscle tension in the HI protocol in blood vessels leads to the occurrence of hyperemia, increasing plasma volume, which may be the reason for a decrease in the IGFBP-3 at POST15." (PMID 36648895, 2022).
Hypsarrhythmia (1 paper, 2025). Hypsarrhythmia is abnormal interictal high amplitude waves and a background of irregular spikes. "Our findings demonstrate that serum IGF-1, IGFBP-3 levels, and their ratio correlate with both hypsarrhythmia severity and short-term ACTH response in IESS patients." (PMID 40371354, 2025). "We compared the serum IGF-1 and IGFBP-3 levels, as well as the IGF-1/IGFBP-3 ratio, between the hypsarrhythmia and non-hypsarrhythmia groups before ACTH treatment." (PMID 40371354, 2025). "We analyzed serum IGF-1, IGFBP-3 levels, and IGF-1/IGFBP-3 ratios in the hypsarrhythmia subgroup before and after ACTH therapy." (PMID 40371354, 2025). "This study examined how serum IGF-1 levels, IGFBP-3 levels, and their ratio relate to EEG hypsarrhythmia and ACTH therapy response in IESS patients, demonstrating the potential clinical value of peripheral IGF-1." (PMID 40371354, 2025). "In this study, among IESS patients in the hypsarrhythmia subgroup, those with higher baseline serum levels of IGF-1, IGFBP-3, and their ratio prior to treatment demonstrated a significantly better response to ACTH therapy." (PMID 40371354, 2025). "Hypsarrhythmia inversely correlated with both serum IGF-1 levels and IGF-1/IGFBP-3 ratios, consistent with previous findings, suggesting that decreased ratios may indicate reduced bioactive IGF-1, thereby worsening hypsarrhythmia." (PMID 40371354, 2025). "The hypsarrhythmia population exhibited significantly lower serum IGF-1 levels and IGF-1/IGFBP-3 ratios (p < 0.05) compared to the non-hypsarrhythmia population." (PMID 40371354, 2025). "Within the hypsarrhythmia population, responders (n = 9) showed higher IGF-1, IGFBP-3 levels, and IGF-1/IGFBP-3 ratios than non-responders (n = 5) before ACTH treatment (p < 0.05)." (PMID 40371354, 2025).
infantile neuronal ceroid lipofuscinosis (1 paper, 2012). A form of neuronal ceroid lipofuscinosis (NCL) characterized by onset during the second half of the first year of life and rapid mental and motor deterioration leading to loss of all psychomotor abilities. "In summary, we have studied the biodistribution and pharmacokinetics of human IGF-1 administrated free or complexed to its natural binding protein IGFBP-3 or nanoparticles in infantile neuronal ceroid lipofuscinosis (INCL) mouse model." (PMID 22778966, 2012).
interstitial cystitis (1 paper, 2021). A rare chronic debilitating urogenital disease characterized by urinary frequency, urgency, and pelvic pain. "On the contrary, IGFBP3 is thought to be increased in patients with interstitial cystitis, and in our paper CYP-induced similar changes in bladder urothelium, ameliorated by AA." (PMID 34072606, 2021).
laryngeal carcinoma (1 paper, 2013). Carcinoma that arises from the laryngeal epithelium. "In our cohort, consisted exclusively of patients with laryngeal cancer, the incorporation of IGFBP3 IHC expression did not improve the prognostic capacity of IGF1R alone." (PMID 23365645, 2013).
lentivirus infection (1 paper, 2020). Virus diseases caused by the Lentivirus genus. "As an infection control, EGFP-overexpressing LNCaP cells were also generated, and it was confirmed that lentivirus infection per se did not induce IGFBP-3 expression." (PMID 32831047, 2020).
leprosy (1 paper, 2011). Leprosy is a chronic infectious disease affecting primarily the skin and peripheral nervous system. "Next, the IGF-I and IGFBP-3 levels in the context of RR episodes, another frequent type of acute inflammatory episode in leprosy, were investigated." (PMID 22166091, 2011). "At the time of leprosy diagnosis, significantly lower levels of circulating IGF-I/IGFBP-3 were found in NR BL and NR LL patients in contrast to NR BT patients and HCs." (PMID 22166091, 2011). "Since the spectral clinical forms of leprosy occur as a result of the capacity of the host to mount anywhere from low- (LL)-to-high (TT) CMI responses against ML, the serum levels of IGF-I and IGFBP-3 were compared among patients having the different clinical forms at the pre-MDT stage." (PMID 22166091, 2011). "In the present investigation, a retrospective study was conducted to compare the circulating levels of IGF-I and IGFBP-3 across the spectral clinical forms of leprosy in conjunction with reactional vs. nonreactional LL and BL patients both at diagnosis and during reaction." (PMID 22166091, 2011).
liver tumor (1 paper, 2012). "Taken together, our results document that long-term reconstitution of IGFBP3 acts as a tumor suppressive factor in pediatric liver tumors." (PMID 22401581, 2012). "Altogether, these data suggest that IGFBP3 downregulation likely has a major role in the vascular invasive and metastatic growth properties of pediatric liver tumors." (PMID 22401581, 2012). "Altogether, these data clearly indicate that restoring IGFBP3 function could dramatically diminish the migratory and invasive properties of liver tumor cells." (PMID 22401581, 2012). "Our finding that IGFBP3 restoration results in reduced tumor cell migration and invasion, while leaving growth and apoptosis merely unaffected, also underscores the assumption that IGFBP3 acts at more advanced stages of liver tumor development in children." (PMID 22401581, 2012). "As IGFBP3 has been described to suppress migration and invasion in several cancers, we desired to determine whether the restoration of IGFBP3 function has any impact on the migratory and invasive capacity of liver tumor cells." (PMID 22401581, 2012). "As we have detected an inverse correlation of TIA1 and IGFBP3, it could be assumed that this suppressive mechanism could act in pediatric liver tumors." (PMID 22401581, 2012). "To assess whether IGFBP3 promoter methylation is clinically relevant, we performed a methylation analysis of our pediatric liver tumor collection using MSP." (PMID 22401581, 2012). "Thus, we determined whether the reintroduction of IGFBP3 into liver tumor cells could change the tumor's biological properties." (PMID 22401581, 2012). "By choosing liver tumor cell lines with high migration rates, namely HepG2 and HUH7, migration assays using collagen-coated transwell inserts demonstrated a significantly decreased migration of tumor cells incubated with recombinant human IGFBP3." (PMID 22401581, 2012).
lumbar disc degeneration (1 paper, 2024). "Some genes are widespread in chondrocyte 4, and chondrocyte 5 may play an important role in the process of lumbar disc degeneration together with the Wnt/Ca2+signaling pathway, such as ANGPTL4, PTGES, IGFBP3, GDF15, TRIB3, and TNFRSF10B." (PMID 38654287, 2024). "ANGPTL4, IGFBP3, PTGES in chondrocytes 4 and TRIB3, GDF15, TNFRSF10B in chondrocytes 5 may play an important role in the lumbar disc degeneration process." (PMID 38654287, 2024).
lumbar disc herniation (1 paper, 2024). "We also found that IGFBP3 was differentially expressed in the peripheral blood of patients with lumbar disc herniation compared with that of healthy controls." (PMID 39328407, 2024). "Meanwhile, we also found a significant increase in the expression of IGFBP3 in the peripheral blood of lumbar disc herniation patients compared to normal individuals." (PMID 39328407, 2024).
metastatic colorectal cancer (1 paper, 2020). "Moreover, the overexpression of IGFBP3 is correlated with better respond rate to first-line chemotherapy and extended time of tumor progression and OS among metastatic colorectal cancer patients without receiving treatment previously." (PMID 33282953, 2020).
minimal change disease (1 paper, 2023). "In patients with FSGS, urinary excretion of IGFBP-3 correlates with disease activity, and urinary levels of IGFBP-3 appear to distinguish FSGS from minimal change disease." (PMID 37331957, 2023).
multinodular goiter (1 paper, 2017). Nodular goiter characterized by more than one discrete tissue mass. "Our study demonstrated that the intranodular IGF-1 and IGFBP-3 levels were significantly higher in the subjects with multinodular goiter compared to single nodules." (PMID 29081797, 2017). "Intranodular IGF-1 and IGFBP-3 levels were significantly higher in the subjects with multinodular goiter compared to single nodules (p = 0.001 and p = 0.043, resp)." (PMID 29081797, 2017). "Intranodular IGF-1 and IGFBP-3 levels were significantly higher in subjects with multinodular goiter compared to the ones with single nodules." (PMID 29081797, 2017).
muscle atrophy (1 paper, 2024). The loss of muscle tissue due to inactivity or disease. "ANGII-induced muscle atrophy is associated with reduced local and systemic insulin-like growth factor 1 (IGF-1) and insulin-like growth factor binding protein 3 (IGFBP3) levels." (PMID 38616362, 2024).
myeloid leukaemia (1 paper, 2024). "It was shown that IGFBP-3 induces the growth arrest and apoptosis of human myeloid leukaemia cells." (PMID 38969699, 2024).
myopia (1 paper, 2023). "Further analysis using an insulin microarray resulted that the levels of insulin and those related factors including IGF2, IGF-2R, IGF binding protein 1 (IGFBP-1), IGFBP-2, IGFBP-3, IGFBP-4 and IGFBP-6 were markedly increased in patients with pathogenic myopia as compared with the controls." (PMID 38203671, 2023).
narcolepsy-cataplexy (1 paper, 2009). "We tested whether this IGFBP3 polymorphism is associated with human narcolepsy-cataplexy by testing 130 trios using the transmission disequilibrium test (TDT)." (PMID 19158946, 2009).
nesidioblastosis (1 paper, 2022). "Of note, prolonged IGFBP3/TMEM219 blockade with ecto-TMEM219 was associated with significant beta-cell expansion, which lead to a significant increase of both islet area and peripheral insulin levels, mimicking nesidioblastosis." (PMID 35115561, 2022).
nodular goiter (1 paper, 2017). Goiter characterized by discrete tissue mass(es) that may or may not produce thyroid hormones. "Our study found that intranodular IGF-1 and IGFBP-3 levels were significantly higher in subjects with multinodular thyroid gland compared to subjects with solitary nodules which may indicate the role of IGF-1 and IGFBP-3 in nodular goiter pathogenesis." (PMID 29081797, 2017).
ovarian endometrioid adenocarcinoma (1 paper, 2021). An endometrioid adenocarcinoma arising from the ovary. "Third, low IGFBP‐3 expression correlates clinically with higher tumor grade, advanced stage, and poor survival in ovarian endometrioid adenocarcinoma patients." (PMID 34485840, 2021).
pancreatic (1 paper, 2020). "Recently, the overexpression of several let-7 downstream targets including HMGA2, IGFBP1, and IGFBP3, were found to define a distinct patient group with poor prognosis in pancreatic cancer." (PMID 32651364, 2020).
panhypopituitarism (1 paper, 2011). Insufficient production of all the anterior pituitary hormones. "Panhypopituitarism can be differentiated from isolated CCH by normal levels of ACTH, cortisol, IGF1/IGFBP3, LH, FSH, and prolactin." (PMID 22606512, 2011). "Panhypopituitarism was excluded by the findings of normal serum levels of ACTH, cortisol, IGF1, IGFBP3, LH, FSH, cortisol excretion in a 24-hour urine, and blood glucose profile." (PMID 22606512, 2011).
parasitic infection (1 paper, 2023). "Production of AREG, EGF, FGF-2, and IGFBP-3 was significantly higher in the intestinal mucosa of colitic mice with parasitic infection than in the intestine of mice without induced disease but infected with H. polygyrus." (PMID 36836678, 2023).
placental insufficiency (1 paper, 2024). Failure of the placenta to deliver an adequate supply of nutrients and oxygen to the fetus. "Fetal hepatocytes cultured under hypoxic conditions undergo a 2.5-fold and 3-fold increase in IGFBP-1 and IGFBP-3 levels, respectively, leading to suggestions that this is the molecular cause for FGR resulting from placental insufficiency." (PMID 38694168, 2024).
polycystic ovary syndrome (1 paper, 2024). A disorder that manifests as multiple cysts on the ovaries. "Analysis of the association between IGF2BP2 and IGFBP3 polymorphisms and the risk of polycystic ovary syndrome (PCOS) was carried out on a total of 300 subjects using both ARMS‐PCR and PCR‐RFLP methods." (PMID 38468402, 2024).
prediabetes (1 paper, 2013). "An alternative pathway, by which IGFBP-3 contributes to BPH development in subjects with prediabetes, could be based on the relationship of adiponectin with BPH development." (PMID 24367483, 2013).
primary hyperoxaluria type 1 (1 paper, 2019). A rare disorder of glyoxylate metabolism characterized by the accumulation of oxalate due to a deficiency of the peroxisomal hepatic enzyme L-alanine: glyoxylate aminotransferase (AGT). "By literature reviewing, among the five genes, four have been well documented in HCC, including: ALDOB, IGFBP3, CYP2E1 and TOP2A, while AGXT was mostly studies in primary hyperoxaluria type 1, there are little reports of AGXT in HCC." (PMID 31771612, 2019). "Among the five genes, four (ALDOB; CYP2E1; IGFBP3; TOP2A) were well documented HCC related genes, while AGXT was mostly studies in primary hyperoxaluria type 1, but had not been reported in HCC." (PMID 31771612, 2019).
proliferative diabetic retinopathy (1 paper, 2013). Advanced retinopathy due to diabetes mellitus characterized by the formation of new vessels in the retina. "Therefore, the present study focused on the assessment of mRNA levels of IGF1, IGF1R, and IGFBP3 both in ERMs and PBMCs from patients with proliferative diabetic retinopathy." (PMID 24379526, 2013).
Pulmonary hypoplasia (1 paper, 2016). "Downregulation of Igfbp3 is associated with nitrofen-induced pulmonary hypoplasia." (PMID 27638768, 2016).
rectal cancer (1 paper, 2019). A primary or metastatic malignant neoplasm that affects the rectum. "In addition to SMAD7 (P = 0.0005) and SMAD3 (P = 0.0003), several other genes or genetic regions (CYP2R1, CHAF1A, CREBBP, IL10, SNPs identified in genome-wide association studies (GWAS) to be associated with IGF levels, IGFBP2/IGFBP5, IGFBP3, and C-MYC region) were associated with rectal cancer." (PMID 31434255, 2019).
renal fibrosis (1 paper, 2025). A final common manifestation of a wide variety of chronic kidney diseases characterized by glomerulosclerosis and tubulointerstitial fibrosis. "Among the differentially expressed proteins, THBS1 and CFHR5 emerged as potential markers of renal fibrosis and complement-mediated glomerular injury, while IGFBP3 reflected growth factor dysregulation associated with both renal and cardiac remodeling." (PMID 41301692, 2025).
renal osteodystrophy (1 paper, 2012). Abnormalities of bone mineral metabolism associated with chronic kidney disease. "Another study showed normal serum IGF-I concentrations, but elevated serum IGFBP-3 concentrations in patients with CKD and different types of renal osteodystrophy compared to healthy control subjects." (PMID 23237568, 2012).
renal tumour (1 paper, 2021). "According to the accumulated GEPIA data, renal tumour tissues expressed higher IGFBP3 levels than normal renal tissues." (PMID 34512163, 2021).